INS (insulin)
Diseases named in the same sentence as INS in open-access papers (continued):
Sharing a sentence is not in itself a finding about the gene and the disease.
metabolic syndrome (continued). "The management of MASLD necessitates a multidisciplinary approach, encompassing strategies such as weight and waist circumference reduction, enhancement of insulin sensitivity, prevention of metabolic syndrome and T2DM, mitigation of MASH, and reversal of fibrosis." (PMID 39904973, 2025). "Exercise helps improve insulin sensitivity, reduce body fat, optimize lipid metabolism, and support cardiovascular function, making it one of the most effective lifestyle interventions for individuals with metabolic syndrome." (PMID 40362807, 2025). "Additionally, a randomized clinical trial involving adults with metabolic syndrome showed that those consuming a breakfast including a 1⁄2 cup of black beans had a better insulin response five hours after the meal compared to those without beans." (PMID 41228468, 2025). "Controlled interventions and cohort studies consistently show that cereal-based diets – especially those high in whole grains and low in rapidly digestible starch – improve insulin sensitivity, reduce postprandial insulin and triglyceride responses, and lower the prevalence of metabolic syndrome." (PMID 41323993, 2025). "Studies have shown that patients with GDM often exhibit dyslipidemia, including elevated triglycerides (TG) and reduced high-density lipoprotein cholesterol, which could contribute to altered insulin sensitivity." (PMID 41323972, 2025). "Since the main trends, such as improvements in insulin sensitivity with pharmacological or dietary interventions and the adverse influence of metabolic syndrome on fertility outcomes, were consistently observed in the low-risk studies as well, the overall interpretations did not materially change." (PMID 40995278, 2025). "Notably, improvements in insulin sensitivity in patients with metabolic syndrome were observed exclusively in the group who received FMT from lean donors or their own gut microbiota." (PMID 41395840, 2025). "Two different randomized clinical trials reported that the combination of omega-3 PUFAs (1200 mg/day to 3000 mg/day, respectively) and lifestyle intervention significantly improved insulin sensitivity, dyslipidemia, and the adiponectin-leptin ratio compared with lifestyle intervention alone." (PMID 40431370, 2025). "In addition to disrupting insulin action in peripheral tissues, these inflammatory responses contribute to the increase of metabolic syndrome T2DM and cardiovascular diseases." (PMID 40013194, 2025). "Data suggests that waist circumference may better indicate central adiposity, insulin sensitivity, and metabolic syndrome, which may be reflected in ALT levels." (PMID 40406225, 2025). "The CCS with a higher fat-to-lean mass ratio (FLR) values demonstrate increased trunk fat, elevated triglycerides, and insulin resistance, alongside lower lean mass and IGF-1 levels-factors that collectively predispose survivors to the risk of metabolic syndrome and cardiovascular issues." (PMID 41374948, 2025). "Dietary live microbes also help attenuate low-grade chronic inflammation, a fundamental pathological mechanism in metabolic syndrome, through their modulation of gut microbiota composition, leading to improvements in insulin sensitivity, lipid metabolism, and vascular function." (PMID 40365238, 2025). "Ginsenoside Rb1 reverses gut microbiota dysbiosis in diabetic mice, alters the levels of free fatty acids in fecal metabolites, increases the abundance of Akkermansia spp., significantly elevates long-chain fatty acid content, improves HFD-induced dyslipidemia, and enhances insulin sensitivity." (PMID 40177494, 2025). "Microbiota-targeted interventions, including prebiotics, probiotics, and fecal microbiota transplantation (FMT), have demonstrated metabolic benefits, with FMT from lean donors significantly improving peripheral insulin sensitivity in individuals with metabolic syndrome." (PMID 41373570, 2025).
metabolic syndrome (continued). "A similar deterioration of adipose tissue function was also described previously in humans, where adipocyte insulin sensitivity was reduced in individuals with metabolic syndrome, with prominent alterations in the lipolysis cascade along with marked downregulation of the IRS2 gene expression." (PMID 41361331, 2025). "This may be because high levels of SF may affect insulin signaling or energy metabolic pathways, thereby exacerbating the difficulty in blood glucose regulation and promoting the development of metabolic syndrome." (PMID 41480537, 2025). "Therefore, beverages sweetened with fructose have been linked to increased de novo lipogenesis, dyslipidemia, and VAT accumulation and reduced insulin sensitivity." (PMID 40944293, 2025). "Furthermore, a significant improvement in metabolic health, indicated by a reduced Met-S score and a lower TyG-WHtR, was noticed (p < 0.001, respectively), reflecting decreased metabolic syndrome severity and enhanced insulin sensitivity." (PMID 41002980, 2025). "Metabolic syndrome, with or without AD, has been associated with impaired brain insulin signaling, including disruptions in IRS-1 and AKT pathways, indicative of a brain insulin-resistant state." (PMID 40964391, 2025). "This transition could mark the point at which atherogenic dyslipidemia begins to exert meaningful effects on reproductive function through mechanisms such as insulin resistance, oxidative stress, and inflammatory processes." (PMID 41257791, 2025). "These drugs, like 2-HOBA, may offer broader metabolic benefits by multiple mechanisms including improving insulin sensitivity and reducing dyslipidemia, potentially contributing to further improvements in liver health." (PMID 40004939, 2025). "Future research relating to metabolic syndrome with larger datasets should continue to analyze potential associations between the MetFlex IndexTM and other common blood metabolite profiles including HDL, HOMA-IR, and fasting insulin." (PMID 40297779, 2025). "The meta-analysis was performed on synthesized data from multiple preclinical studies examining the effects of kefir interventions on metabolic syndrome (MetS)-related parameters, including weight gain, lipid profiles, plasma glucose, and insulin levels in both mouse and rat models." (PMID 40565686, 2025). "An obvious high glucose, low insulin level and dyslipidemia were observed in our model, so just a high glucose treatment of cardiomyocytes in vitro experiment may exist a certain degree of difference with complex pathomechanisms of DCM." (PMID 38790051, 2024). "Collectively, these findings underscore the complex interplay between mitochondrial dysfunction, lipid and amino acid metabolism, and insulin signaling, emphasizing the need for a multifaceted therapeutic approach to address the diverse aspects of metabolic syndrome." (PMID 38744846, 2024). "In another randomized, controlled trial in men with metabolic syndrome, nasoduodenal tube-facilitated Allo-FMT derived from lean individuals was associated with improved insulin sensitivity and increased microbial diversity compared to individuals who received Auto-FMT after 6 weeks of intervention." (PMID 39200335, 2024). "CCN5/WISP2 limits adipocyte differentiation in abdominal subcutaneous adipose tissue; reduced expression is linked to adipose hypertrophy associated with metabolic syndrome, while overexpression increases insulin sensitivity and is protective against metabolic syndrome." (PMID 39401200, 2024). "The administration of PTP in C57BL/6J mice inhibited the HFD-induced abnormal weight gain, visceral obesity, and dyslipidemia, and also improved insulin sensitivity, as revealed by the improved insulin tolerance and the decreased glucose levels during an insulin sensitivity test." (PMID 39063332, 2024). "Dyslipidemia may impact pancreatic function and insulin sensitivity through various pathways, promoting the progression of prediabetes and T2DM." (PMID 38628590, 2024).
metabolic syndrome (continued). "Significantly higher mean FI levels in obese than non-obese subjects point towards excessive insulin production due to IR, a hallmark of metabolic syndrome (p-value <0.001, S)." (PMID 38770513, 2024). "The propensity of insulin to contribute to dyslipidemia, atherosclerosis, hypertension, heart failure, and arrhythmia may lower the safety profile of insulin." (PMID 39262558, 2024). "Insulin-resistant cells cannot properly respond to insulin or use glucose from the blood and the resulting disturbances in lipid and glucose metabolism stimulate the further development of metabolic inflammation and metabolic syndrome (MS)." (PMID 39767388, 2024). "Tirzepatide displayed an unprecedented glucose and body weight lowering potential, presenting also with the ability to increase insulin sensitivity, reduce systolic blood pressure and inflammation and ameliorate dyslipidemia, particularly by reducing triglycerides levels." (PMID 38472620, 2024). "However, during compensatory hyperinsulinemia in IR patients, alterations in insulin secretion or clearance result in mild forms of glucose intolerance, dyslipidemia, and hypertension." (PMID 38629096, 2024). "Despite the strong association of UA and ALB levels with cardiovascular diseases, supported by previous scientific evidence, there exist some controversies regarding the factors that affect UA and ALB concentration such as malnutrition, insulin, gout, diet, renal diseases, and metabolic syndrome." (PMID 38269629, 2024). "Betulinic acid could enhance insulin sensitivity, and alleviate the blood glucose, inflammation, dyslipidemia and oxidative stress in high-fructose diet-induced metabolic syndrome by activating PI3K/Akt signal pathways." (PMID 39063310, 2024). "The mechanisms of muscle weakness associated with metabolic syndrome are not completely clear but are related to inflammation and insulin resistance." (PMID 38709150, 2024). "To summarize, the enhanced TyG index observed in breast cancer sufferers may aggravate the evolving procedure of breast cancer depending on various mechanisms, including insulin signaling pathways, dyslipidemia, and altered energy metabolism." (PMID 38279158, 2024). "Relative to olive oil, distinctions in gut microbiota modulation of mice, rats, or grouper have also been discovered in soybean oil, coconut oil, corn oil, and peanut oil as exerted increase insulin sensitivity and prevent fatty liver, attenuate metabolic syndrome, and improve gut health activities." (PMID 39403395, 2024). "LBW animals may have an increased risk of metabolic diseases, such as impaired glucose utilization and insulin sensitivity, dyslipidemia, and oxidative stress." (PMID 38596462, 2024). "In addition to fatty liver disease and liver iron overload, dolphins with metabolic syndrome have elevated insulin (13 ± 13 μIU/mL), glucose (108 ± 12 mg/dl), triglycerides (128 ± 45 mg/dl), and total cholesterol (217 ± 51 mg/dl)." (PMID 39057678, 2024). "Vitamin D3 supplementation may offer favorable impacts on metabolic syndrome, including enhanced insulin sensitivity, decreased levels of glucose and insulin, reduced blood lipids, and diminished inflammation." (PMID 38732523, 2024). "It has been shown that IR and dysregulation of insulin signalling play a critical role in the development of metabolic syndrome by initiating the pathophysiology of metabolic syndrome through induction of glucolipotoxicity, impairment of glucose disposal and triggering of pro‐inflammatory response." (PMID 39644152, 2024). "Currently, it is unknown whether the dyslipidemia observed is secondary to changes in insulin signaling and examining changes over the course of pregnancy would address these questions." (PMID 39667808, 2024).
metabolic syndrome (continued). "Since skeletal muscles play a pivotal role in insulin sensitivity, sarcopenic patients are prone to the progression of metabolic syndrome, which may impair the functionality of the esophagus and stomach as mechanical barriers, thus precipitating GERD." (PMID 39050602, 2024). "While 3xTg-AD female mice are considered more susceptible to insulin-related metabolic syndrome, our ITT results did not reveal any significant differences between the 3xTg-AD and control mice, with no noticeable impact from curcumin supplementation." (PMID 38257133, 2024). "Furthermore, the higher insulin levels and lower insulin sensitivity found in WD-fed male mice are concordant with the obvious overweight phenotype and fatty liver appearance, as well as clear dyslipidemia, at 24 weeks of age." (PMID 39330437, 2024). "Moreover, fructose restriction in obese children with metabolic syndrome improved lipid profiles and insulin sensitivity." (PMID 38247511, 2024). "This inflammation appears to be particularly related to metabolic syndrome and insulin sensitivity." (PMID 38421551, 2024). "Peripheral IR in the metabolic syndrome triggers lipolysis and increasing circulating free‐fatty acids which promote neuronal oxidative stress and mitochondrial dysfunction by inhibiting neuronal insulin signalling." (PMID 39644152, 2024). "It was initially explained by the “two-hit” hypothesis, which proposed that the first “hit” involves steatosis stimulated by factors such as sedentary lifestyle, metabolic syndrome, and insulin insensitivity." (PMID 38892602, 2024). "Steatosis from de novo lipogenesis in the liver, as well as influx of fatty acids from peripheral tissue (as seen in metabolic syndrome, insulin insensitivity, and obesity), leads to lipotoxicity, which promotes hepatocyte apoptosis and the release of damage associated molecular patterns (DAMPs)." (PMID 38892602, 2024). "Potential treatments could focus on, among others, two important common pathological pathways of metabolic syndrome and Alzheimer’s Disease: inflammation and insulin resistance." (PMID 39350374, 2024). "Additionally, studies have focused on translating fecal microbiota from lean donors to recipients with metabolic syndrome to enhance insulin sensitivity." (PMID 38792581, 2024). "Dyslipidemia may impact pancreatic function and insulin sensitivity through various pathways, thereby promoting the progression of prediabetes and T2DM." (PMID 38628590, 2024). "Similarly, a systematic review of 20 studies investigating the effects of a KD on metabolic syndrome criteria reported that most of the included studies showed significant changes in glucose, insulin, HOMA-IR, and HbA1C levels after the intervention." (PMID 39770995, 2024). "Moreover, glucocorticoids trigger hepatic gluconeogenesis, and inhibit or generate an insulin effect on skeletal muscle and adipose tissue, respectively, thus promoting visceral adiposity and the metabolic syndrome." (PMID 39062927, 2024). "Furthermore, allogeneic FMT derived from donors with metabolic syndrome feces led to reduced insulin sensitivity in metabolic syndrome recipients compared to those utilizing donors post-Roux-en-Y gastric bypass surgery." (PMID 39735647, 2024). "Indeed, taurine supplementation has shown in earlier studies to increase insulin sensitivity, normalize blood glucose level, down-regulate hyperinsulinemia, control hypertension, and control dyslipidemia." (PMID 38637413, 2024). "Notably, PPARα agonists are known for their significant role in the treatment of dyslipidemia or metabolic syndromes by reducing plasma triglyceride levels together with the modulation of glucose homeostasis and insulin resistance." (PMID 38611871, 2024).
metabolic syndrome (continued). "Saccharina japonica showed both anti-inflammatory (leading to increased zebrafish larvae’s survival rate and health) and metabolic health-promoting activities (evidenced by a decrease in dyslipidemia, liver, and renal injury, while increasing insulin sensitivity and gut microbiota health)." (PMID 38675719, 2024). "Adiponectin regulates insulin sensitivity, and it has anti-inflammatory, antioxidant, and cardioprotective properties; thus, low levels of this adipokine have an important role in the development of metabolic syndrome." (PMID 39771030, 2024). "Furthermore, high dietary intake of L-arg originating from plant sources has been related to lower serum insulin levels, HOMA-IR values, and decreased risk of developing metabolic syndrome." (PMID 38674919, 2024). "Moreover, additional research has illustrated a correlation between an increased body mass index (BMI), hip and waist circumference, and insulin levels, the key components in metabolic syndrome, with the severity of psoriasis disease." (PMID 39202262, 2024). "It is unclear how gastrointestinal ENaC may contribute to the metabolic syndrome phenotype; however, ENaC is regulated by insulin and thus may contribute to intracellular signaling affecting glucose utilization within the gut." (PMID 39224121, 2024). "It therefore remains to be seen whether treatment with metformin during pregnancy alone or in addition to insulin attenuates the risk of developing AGT and metabolic syndrome in the future." (PMID 38328480, 2024). "Sucralose has been implicated in altering lipid metabolism, potentially leading to adverse effects such as increased fat storage and reduced insulin sensitivity, both of which may contribute to dyslipidemia." (PMID 39015535, 2024). "Parental obesity has been found to associate with disturbances in trace elements (i.e., copper, zinc, iron, selenium), which could predispose to exacerbate related comorbidities, such as altered insulin homeostasis, dyslipidemia, and inflammation." (PMID 38238301, 2024). "An aberrant somatic response to stress could contribute to metabolic syndrome (increased abdominal fat, insulin dysregulation, dyslipidemia, hypertension) with a consequent increase in cardiovascular risk (stroke, infarction)." (PMID 39596351, 2024). "The authors suggested that lipid catabolites may allow early detection of the metabolic syndrome, as their blood concentrations vary depending on the interaction between insulin sensitivity and lipid metabolism." (PMID 38114521, 2023). "Overall, our study suggests that daily tree nut consumption reduces metabolic syndrome risk without the requirement of caloric restriction, potentially by improving waist circumference, lipid biomarkers, and insulin sensitivity." (PMID 38140310, 2023). "FMT, as an adjunctive therapy, does not produce any serious adverse effects and may be useful in the treatment of metabolic syndrome, especially in improving HbA1c, insulin sensitivity, and HDL cholesterol." (PMID 37471410, 2023). "Other studies have also shown that FMT from lean donors can have a temporary positive effect on insulin sensitivity in obese individuals with metabolic syndrome, without causing significant changes in other metabolic parameters." (PMID 37280680, 2023). "The hormonal changes can trigger a cascade of events that lead to tissue resistance to insulin, ultimately contributing to the development of metabolic syndrome, cardiovascular diseases, proinflammatory alterations, and prothrombotic changes, resulting in increased morbidity." (PMID 38132215, 2023). "Initially, it was postulated that adrenal incidentaloma was a new manifestation of the metabolic syndrome that might result from insulin-mediated stimulation." (PMID 36468929, 2023). "In addition, insulin can also activate MAPK pathways but inappropriate MAPK signaling contributes to the development of metabolic syndrome and T2DM." (PMID 36891054, 2023).